RNF225 (ring finger protein 225)
Tractability: Antibody: UniProt predicts a signal peptide or a membrane-spanning region.
Gene: Protein-coding gene on chromosome 19 (58,395,656 to 58,397,079, forward strand). Ensembl gene ENSG00000269855.
Subcellular location: Membrane
Gene Ontology:
Molecular function: ubiquitin protein ligase activity
Biological process: protein ubiquitination
Cellular component: membrane
Genetic constraint (gnomAD): Loss-of-function variants: 1 observed, 1.53 expected, observed/expected ratio (o/e) 0.66, 90% interval 0.21 to 1.83. That is too few expected variants to judge how well the gene tolerates losing a copy. Missense variants: 510 observed, 430.82 expected, observed/expected ratio (o/e) 1.18, 90% interval 1.1 to 1.27. Synonymous variants: 295 observed, 227.97 expected, observed/expected ratio (o/e) 1.29, 90% interval 1.18 to 1.42.
Homologues: Orthologues: chimpanzee RNF225 (98% identical), dog RNF225 (81% identical), mouse Rnf225 (74% identical), rabbit RNF225 (73% identical), rat Rnf225 (73% identical), tropical clawed frog rnf225 (25% identical). Paralogues in human: RNF223 (22% identical), RNF183 (15% identical), RNF208 (13% identical).